LRRC34 (leucine rich repeat containing 34)
Description:
Highly expressed in stem cells where it may be involved in regulation of pluripotency. In embryonic stem cells (ESCs), important for normal expression of the pluripotency regulators POU5F1/OCT4 and KLF4. Also important for expression of the ectodermal marker gene NES and the endodermal marker gene GATA4. Promotes stem cell proliferation in vitro.
Synonyms: MGC27085
Tractability: Small molecule: a structure with a bound ligand is known. PROTAC: ubiquitination databases record sites on it.
Gene: Protein-coding gene on chromosome 3 (169,793,003 to 169,812,986, reverse strand). Ensembl gene ENSG00000171757.
Subcellular location: Nucleus; Nucleus, nucleolus; Cytoplasm
Subcellular location (Human Protein Atlas): Microtubules; Basal body; Cytokinetic bridge; Mitotic spindle; Primary cilium
Gene Ontology:
Biological process: telomere maintenance
Cellular component: cytoplasm; nucleus; nucleolus
Genetic constraint (gnomAD): Loss-of-function variants: 29 observed, 34.34 expected, observed/expected ratio (o/e) 0.84, 90% interval 0.63 to 1.15. The upper end of that interval is the gene's LOEUF score, 1.15, which puts it in group 5 of 6, group 1 being the genes least tolerant of losing a copy. Missense variants: 407 observed, 439.64 expected, observed/expected ratio (o/e) 0.93, 90% interval 0.85 to 1. Synonymous variants: 157 observed, 158.06 expected, observed/expected ratio (o/e) 0.99, 90% interval 0.87 to 1.13.
Homologues: Orthologues: chimpanzee LRRC34 (99% identical), macaque LRRC34 (95% identical), dog LRRC34 (78% identical), rabbit LRRC34 (77% identical), guinea pig LRRC34 (74% identical), pig LRRC34 (70% identical), rat Lrrc34 (70% identical), mouse Lrrc34 (69% identical), tropical clawed frog lrrc34 (47% identical), zebrafish lrrc34 (44% identical).
Diseases named in the same sentence as LRRC34 in open-access papers:
LRRC34 is named in the same sentence as 6 diseases in open-access papers, as found by Europe PMC text mining. Sharing a sentence is not in itself a finding about the gene and the disease. The quoted sentences say what the papers report.
adenoma (1 paper, 2024). A neoplasm arising from the epithelium. "Interestingly, three stemness/differentiation-related genes, including LRRC34, CEBPB, and TBX3, showed significant changes in their expression levels in adenoma compared to normal colon mucosa." (PMID 38670944, 2024).
ciliopathies (1 paper, 2022). "Finally, several factors related to ciliopathies such as DNALI1, DNAAF1, CCDC65, CCDC39, and LRRC34 were strongly reduced already at P17 (14–31% of wild-type level)." (PMID 36611846, 2022).
melanoma (1 paper, 2024). A malignant, usually aggressive tumor composed of atypical, neoplastic melanocytes. "Genes in cluster 8 (GSTO2, LRRC34), 9 (CLPTM1L) and 10 (CTSS, SETDB1, ANXA9, GOLPH3L, HORMAD1, PPIL3, CASP9, ALS2CR12) underlie the association between melanoma and cancers." (PMID 38308491, 2024).
multiple myeloma (1 paper, 2021). "The changes at the PTM site might alter the structure of LRRC34 protein, which may lead to multiple myeloma." (PMID 34373545, 2021).
cancer (2 papers, 2021 to 2024). A tumor composed of atypical neoplastic, often pleomorphic cells that invade other tissues. "Three nsSNPs; rs1126809 (TYR), rs10936600 (LRRC34), and rs757978 (FARP2), were found as the most damaging cancer pathogenic variants." (PMID 34373545, 2021). "As TYR, LRRC34, and FARP2 genes play important roles in numerous cellular processes such as cell proliferation, differentiation, growth, and cell survival; therefore, any impairment on the protein function could be involved in the development of cancer." (PMID 34373545, 2021).
tumor (1 paper, 2025). "In TRACERx tumor tissues, we observed evidence for methylation-dependent dosage compensation in LRRC34 when co-amplified with the PI3KCA oncogene in both tumor PDCs." (PMID 40931149, 2025).